SCN1A (sodium voltage-gated channel alpha subunit 1)
Diseases named in the same sentence as SCN1A in open-access papers (continued):
Sharing a sentence is not in itself a finding about the gene and the disease.
generalized epilepsy (47 papers, 2009 to 2025). Epilepsy that is characterized by generalized seizure types and may have typical interictal and/or ictal EEG findings that accompany generalized seizure types (for example generalized spike-wave). "EPBL-0094 presented with generalized epilepsy and learning disability and was found to have a heterozygous de novo splice site variant in SCN1A (c.2383-2A>C) (pathogenic)." (PMID 40565278, 2025). "For instance, the sodium channel 1 subgroup (SCN1B) is located on the 19th chromosome, while the 1 subgroup (SCN1A) resides on the 2nd chromosome; both have been identified as defective in cases of generalized epilepsy associated with febrile convulsions." (PMID 40647621, 2025). "Mutations in the SCN1A gene can cause a variety of phenotypes, ranging from mild forms, such as febrile seizures and generalized epilepsy with febrile seizures plus, to severe, such as Dravet and non-Dravet developmental epileptic encephalopathies." (PMID 36231081, 2022). "We also found that SCN1A mutations were associated with FS, generalized epilepsy with FS plus (GEFS+), and DS." (PMID 31139143, 2019). "In addition, mutations in the SCN1A gene are also known to cause generalized epilepsy with febrile seizures plus (GEFS+)." (PMID 40565516, 2025). "We also conducted another research on the spectrum of generalized epilepsy with febrile seizure plus (GEFS+) focusing on clinical manifestations and SCN1A gene mutations." (PMID 38649973, 2024). "Generalized epilepsy with febrile seizures plus (GEFS+) is a common childhood-onset genetic epilepsy syndrome, often caused by a mutation in the human Nav channel gene SCN1A." (PMID 27844061, 2016). "The genes SCN1A, SCN2A coding for the alpha subunit have been linked to specific idiopathic epilepsy syndromes such as generalized epilepsy with febrile seizures plus (GEFS+) and benign familial neonatal-infantile seizures (BFNIS), respectively." (PMID 25893123, 2015). "The SCN1A gene has so far been well studied in large series of patients with severe myoclonic epilepsy or in families with idiopathic generalized epilepsies and febrile seizures plus (GEFS+) and also in some families with febrile seizures." (PMID 21713554, 2011). "Moreover, similar findings were described in a German study where SCN1A-A3184G polymorphism was not considered as a major contributor to the idiopathic generalized epilepsy." (PMID 36056404, 2022).
epilepsy syndrome (46 papers, 2011 to 2026). A syndrome that has a characteristic cluster of clinical features and/or lectroencephalographic (EEG) findings that reflect underlying epileptic activity. "Pathogenic variants in the SCN1A gene are among the most common identified genetic causes of most severe childhood epileptic syndromes—DEEs—now recognized as two phenotypically different groups: DRVT and non-Dravet DEEs (NDEEMA, EIDEE/MD, EIDEE)." (PMID 36231081, 2022). "The SCN1A gene encodes the alpha 1 subunit of the voltage-gated Na+ channel and plays a crucial role in the pathogenesis of several epilepsy syndromes." (PMID 36506519, 2022). "Among these genes, SCN1A (14.9%, 7/47) was most frequently associated with epilepsy syndromes, such as DS and general febrile seizures (FS)." (PMID 31139143, 2019). "SCN1A has more than 40 missense mutations that are known to be linked to an epilepsy syndrome termed “genetic epilepsy with febrile seizures plus” (GEFS+)." (PMID 29997502, 2018). "In this study, we investigated the liability of SCN1A variants that were previously classified as pathogenic, in a cohort of common epilepsy syndromes." (PMID 26990884, 2016). "SCN1A mutations can also be found in a few other epilepsy syndromes that show some clinical similarities to DS, such as myoclonic atonic epilepsy (MAE) and genetic epilepsy with febrile seizures plus (GEFS+)." (PMID 27465585, 2016). "Mutations in SCN1A are associated with a spectrum of epilepsy syndromes; a few mutations result in FHM." (PMID 21713554, 2011). "Specifically, the heat-induced paralysis observed in these flies was reminiscent of heat-induced seizures observed in flies carrying pathogenic variants in the SCN1A-analogous fly gene para (paraGEFS+ or paraDS), which mimic SCN1A-associated epilepsy syndromes." (PMID 41017589, 2025). "Phenotypic heterogeneity is a hallmark of SCN1A-related epilepsies, not only because of the variety of epileptic syndromes that can result from a pathogenic variant in SCN1A but also because the same SCN1A variant can lead to different epileptic disorders and degrees of phenotypic severity." (PMID 36715146, 2023). "The SCN1A gene has a causative role in some epilepsy syndromes (severe myoclonic epilepsy and GEFS+) and has recently been associated with new and different clinical phenotypes, such as focal and generalized cryptogenic epilepsy and atypical Panayiotopoulos syndrome." (PMID 21713554, 2011). "However, predicting the outcome of de novo missense SCN1A mutations is difficult, since milder epileptic syndromes may also be associated." (PMID 30735520, 2019). "Our findings expand the spectrum of SCN1A variants associated with GEFS+ and highlight the importance of comprehensive pedigree analysis in deciphering the genetic basis of heterogeneous epilepsy syndromes." (PMID 41788412, 2026). "Sodium channelopathies are genetic disorders caused by mutations in genes, including sodium voltage-gated channel alpha subunit 1 (SCN1A), that lead to several epilepsy syndromes." (PMID 39165469, 2024). "In the case of SCN1A, despite being probably the single most important gene in epilepsy, both responsible for multiple epileptic syndromes and the target of several experimental gene-based therapies, little is known about its regulatory landscape." (PMID 36715146, 2023). "The SCN1A-related disorders form a broad phenotypic spectrum of epileptic and non-epileptic syndromes." (PMID 36231081, 2022). "In addition to DS, the broad phenotypic spectrum of SCN1A-related epilepsies includes febrile seizures (FS) alone, genetic epilepsy with FS plus (GEFS+) and other epilepsy syndromes, frequently associated with significant comorbidities." (PMID 36715146, 2023). "Overall, we highlight the ambiguities of variant classification in common epilepsy syndromes and emphasize that the majority of SCN1A variants could not be re-classified as pathogenic." (PMID 26990884, 2016).
epilepsy syndrome (continued). "Similarly, individual AD9 has dystonia and seizures and a duplication encompassing three genes, CACNB4, SCN1A and SCN2A, each responsible for epilepsy syndromes with or without movement disorders." (PMID 36781956, 2023).
febrile seizures (41 papers, 2009 to 2025). "SCN1A variants have also been implicated in simple febrile seizures (FS), which are convulsive seizures triggered by fever occurring between 6 months and 6 years of age." (PMID 37654020, 2024). "The common SCN1A single nucleotide polymorphism rs3812718, affecting splicing, has also been associated with febrile seizures, though replication has failed." (PMID 24014518, 2013). "Pathogenic variants of the SCN1A gene result in a wide range of disease severities, from severe DS, on one end of the spectrum, to milder pathologies on the other end, such as genetic epilepsy with febrile seizures plus (GEFS+) and the genetic syndrome with febrile seizures (FS or FS+)." (PMID 36119672, 2022).
developmental and epileptic encephalopathy (35 papers, 2019 to 2026). An epilepsy associated with developmental impairment that may be due to either the underlying etiology or the superimposed epileptic activity, or both. "DS is known to be a rare, severe, and refractory developmental and epileptic encephalopathy, with over 90% of DS patients who having a pathogenic mutation in SCN1A gene." (PMID 39045432, 2024). "Mutations in the SCN1A gene represent the most commonly identified cause of developmental and epileptic encephalopathies (DEEs) also among Polish patients." (PMID 38785537, 2024). "Mutations in SCN1A, SCN2A, SCN3A, and SCN9A genes are known to cause autosomal dominant developmental and epileptic encephalopathies, with haploinsufficiency as a primary mechanism." (PMID 40894531, 2025). "DS is a developmental and epileptic encephalopathy (DEE) caused by mutation in SCN1A gene." (PMID 40740850, 2025). "SCN1A variants have recently been implicated in a form of DEE considered more severe than DS, known as early infantile developmental and epileptic encephalopathy (EIDEE)." (PMID 37139072, 2023). "SCN1A-related Dravet syndrome is an early onset developmental and epileptic encephalopathy characterized by multiple seizure types, cognitive decline, behavioral disturbances, and ataxia." (PMID 35414300, 2023). "Our survival analysis indicated SUDEP first occurred after two months of age in both male and female mutants, which is four to six weeks later than common monogenic developmental epileptic encephalopathy SUDEP models, such as Scn1a, Scn8a and Kcna1 mutants." (PMID 34396109, 2021).
autism (30 papers, 2012 to 2025). Persistent deficits in social interaction and communication and interaction as well as a markedly restricted repertoire of activity and interest as well as repetitive patterns of behavior. "A recent study of 134 cases of autism identified 16 variants and 12 genes with evidence of pathogenicity, including three SCN1A mutations." (PMID 35002916, 2021). "On the contrary, heterozygous loss-of-function mutations in the SCN1A gene provoke severe myoclonic epilepsy in infancy in which patients have autism-spectrum behaviors." (PMID 32899972, 2020). "For example, one of the genes identified is SCN1A, which encodes a voltage-gated sodium channel, is one of the genes identified to be frequently mutated in autism." (PMID 29483624, 2019). "The NaV1.1 (SCN1A) locus was identified as indicating susceptibility to autism during genome-wide association studies." (PMID 31933626, 2019). "Both FHM3 and autism alleles of SCN1A perturb calmodulin-interacting intracellular regions of the channel protein." (PMID 24204377, 2013). "It is particularly intriguing that the autism-associated SCN1A alleles are quite different from the seizure alleles, which produce a more severe lesion in the channel protein, but that they are very similar to the mutations found in the FHM3 families." (PMID 24204377, 2013). "It was suggested that the autism-related traits in DS mice might be caused by a decrease in inhibitory neurotransmission in GABAergic interneurons due to SCN1A haploinsufficiency providing further evidence that impaired GABAergic signaling may underlie ASD." (PMID 24605088, 2014). "An autism-like phenotype that includes seizures and social deficits can be established in mice through selective haplodeletion of the Na+V1.1 ion channel-encoding SCN1A gene in forebrain GABAergic interneurons." (PMID 24717046, 2014). "Intriguingly, rare mutations within genes encoding similar α subunits, such as SCN1A, SCN2A and SCN3A, have been linked to autism." (PMID 24564958, 2014). "This gene lies adjacent to SCN1A within the sodium channel gene cluster at the autism-5 locus (AUT5) on chromosome 2." (PMID 24204377, 2013). "A previous study identified four missense mutation in SCN1A gene, one coding mutation in SCN2A gene from different autism families and suggested that mutations in the sodium channel genes may play a role in autism susceptibility." (PMID 22848613, 2012). "However, no headache symptomatology was reported in association with autism for SCN1A or ATP1A2 genes, although we do not know if it was investigated." (PMID 32899972, 2020). "Other examples of mouse models to study characteristics of ASD include Purkinje-specific knock out of TSC1, chromosome-engineered mouse model for human 15q11-13, model for 16p11.2 lesion found in autism, 22q11.2 mice lacking PTEN, CNTNAP2, SHANK2, and SCN1A." (PMID 24605088, 2014).
channelopathies (28 papers, 2014 to 2026). "Our data highlight the importance of addressing the associated comorbidities and ultimately the underlying SCN1A channelopathy to improve quality of life for affected individuals and their carers/families." (PMID 38229878, 2024). "In the case of six patients with variants in other channelopathy-related genes (SCN1A, SCN2A, SCN8A, and KCNQ2), the previous literature guided the choice of anti-seizure medication." (PMID 37645600, 2023). "The underlying channelopathy pathway accounted for 46.7% (7/15) of the monogenic variants, including ion channel genes (SCN1A, KCTD7, KCNC1, CACNA1A, KCNMA1) and ligand-gated ion channel genes (GABRA1, GABRG2)." (PMID 36034301, 2022). "Mutations in the SCN1A gene are responsible for a plethora of diseases, collectively known as channelopathies affecting the entire nervous system." (PMID 35625812, 2022). "Previous studies have shown that the biophysical properties of channelopathy-causing variants, such as SCN1A, KCNA2, KCNQ2, and GluN2B may correlate with phenotypes." (PMID 35845605, 2022). "Furthermore, the association between EIDEE and SCN1A gain-of-function points toward alternative mechanisms for hyperexcitability in SCN1A channelopathies, and while gain-of-function is observed in both FHM3 and EIDEE their clinical consequences differ dramatically." (PMID 37139072, 2023). "Shared genetic mutations, particularly in genes encoding ion channel subunits such as CACNA1A, SCN1A, and ATP1A2, further support a common channelopathy model." (PMID 40949139, 2025). "When grouping genes into well‐defined functional categories, a ≥50% seizure reduction was achieved in nine of 18 (50%) non‐SCN1A channelopathies." (PMID 40126049, 2025). "Several genes, especially channelopathies, have been identified in patients who died of SUDEP including gene variants associated with seizures (e.g., SCN1A, SCN8A, SCN2A) or long QT-Syndrome (SCN5A, KCNH2, KCNQ1)." (PMID 40703772, 2025). "Twenty-five patients (12 males, 13 females; mean age at referral: 4.5 years; 6 months–31 years), from 24 unrelated families, received a diagnosis of an SCN1A-related channelopathy." (PMID 38891831, 2024). "Here, we provide a brief overview of the genetic basis and clinical features of SCN1A channelopathies, and then consider their impact upon neuronal and neural circuit function." (PMID 37139072, 2023). "In other channelopathies, such as SCN1A-related disorders, treatment paradigms vary significantly depending on whether a variant leads to LOF or GOF." (PMID 41289009, 2026). "Also, from a practical point of view, significant differences in rheobase and the RRP may suggest that NESs can be used in differential diagnostics of SCN1A channelopathies before genetic testing." (PMID 38339022, 2024). "Among molecularly diagnosed cases SCN1A, SCN2A, KCNQ2, SCN8A, and ATP1A2 were identified as channelopathy-related genes, representing 7 patients." (PMID 40083435, 2025). "Lack of agents directly targeting SCN1A dysfunction/Nav1.1 channelopathy: No current drug corrects the impaired GABAergic interneuron function caused by NaV1.1 channel deficits." (PMID 40772259, 2025).
cognitive deficits (28 papers, 2009 to 2025). "For instance, the same heterozygous variant (c.1498C>T; p.Arg500Trp) in the SCN1A gene has been reported in a patient with refractory seizures and cognitive impairment." (PMID 39568674, 2024). "Heterozygous loss of the 1b interval appears to have a less severe impact compared to truncating Scn1a mutations, which are sufficient to reduce survival and cause behavioral and cognitive deficits relevant to DS and NDD in mice." (PMID 33910599, 2021). "We focused on hippocampus as an example P32 tissue, as hippocampal ablation of Scn1a has been specifically linked to seizure and DS-relevant cognitive deficits in mice." (PMID 33910599, 2021). "This lifelong epilepsy disorder is caused in the majority of cases by mutations in the gene SCN1A, coding for the voltage-gated sodium channel Nav1.1, and is characterized by both seizures and severe cognitive impairment." (PMID 26978272, 2016). "Current antiepileptic drugs often fail to protect against the severe seizures and behavioral and cognitive deficits found in patients with SCN1A mutations." (PMID 27799911, 2016). "Scn1a+/- mice show both cognitive deficits and autistic traits that are caused by impaired GABAergic neurotransmission and can be rescued by drug treatment." (PMID 24355397, 2013). "These short-term effects may herald more consequential behavioral and cognitive deficits reported in Scn1a-deficient mouse models." (PMID 37551713, 2023). "In this study, we showed that efficient restoration of Scn1a gene expression in a DS mouse model after symptom onset, can suppress seizures together with the associated severe behavioral alterations including hyperactivity, social interaction impairment and cognitive defects." (PMID 35013317, 2022). "It has also been demonstrated that enhancement of GluN2A activity ameliorates seizure activity and cognitive deficits in SCN1A knock‐in mice." (PMID 40944498, 2025). "Findings from Scn1a knockdown studies in the medial septum and diagonal band of Broca (MSDB) further illustrate how gene-specific effects can produce selective cognitive deficits." (PMID 41585885, 2025). "Besides, Scn1a knockout mice demonstrated cognitive impairment even without seizures." (PMID 33985586, 2021).
Ataxia (27 papers, 2009 to 2025). Ataxia refers to impaired coordination of voluntary muscle movement. "For example, homozygous Scn1a knockout mice develop ataxia and die at 15 days postnatal, whereas heterozygous Scn1a deficient mice show seizure activity and early mortality starting at 3 weeks of age." (PMID 31025941, 2019). "In mice, heterozygous loss-of-function mutation in Scn1a (Scn1a+/-), reproduces several of the symptoms associated to the human mutation, such as thermally induced and spontaneous seizures, premature death, ataxia and sleep disorder." (PMID 24355397, 2013). "Homozygous Scn1a knockout mice develop ataxia and die at 15 days postnatal, whereas heterozygous Scn1a-deficient mice show seizure activity and early mortality starting at 3 weeks of age." (PMID 40650012, 2025). "Brain sodium channelopathies, which include mutations in SCN1A, SCN2A, SCN3A, and some mutations in SCN8A observed in cases of familial human ataxia and in mice models of ataxia and end-plate diseases (these genes encode the channels NaV1.1, NaV1.2, β1-subunit, and NaV1.6 respectively)." (PMID 22798951, 2012).